CCL11 (C-C motif chemokine ligand 11)
Diseases named in the same sentence as CCL11 in open-access papers (continued):
Sharing a sentence is not in itself a finding about the gene and the disease.
COVID-19 (49 papers, 2020 to 2025). A disease caused by infection with severe acute respiratory syndrome coronavirus 2. "Brain fog is a common symptom of long COVID and has been associated with elevations of CCL11, a specific cytokine that was found to be increased in the plasma of COVID-19 patients who presented with cognitive dysfunction." (PMID 40400794, 2025). "Elevated CCL11 levels are seen in COVID-19 patients and associated with aging and dementia, learning and memory impairments, and reduced neurogenesis." (PMID 39660133, 2024). "In mice, alterations in hippocampal neurogenesis and reductions in oligodendrocytes and axon myelin were observed, accompanied by elevated levels of cerebrospinal fluid (CSF) cytokines, particularly eotaxin-1 (CCL11), which were associated with cognitive symptoms in COVID-19 patients." (PMID 40542011, 2025). "CCL11 is widely recognized as a biomarker of neuroinflammatory disorders, including multiple sclerosis, Parkinson’s disease, Alzheimer’s disease, and COVID-19–associated neurological syndromes, and warrants further investigation into its involvement in USUV-associated neuropathogenesis." (PMID 41472308, 2025). "However, for patients with moderate to severe risk for OSA with concurrent COVID-19, there is a decrease in serum IL-6, Eotaxin-1/CCL11, and salivary MIP-3α/CCL20." (PMID 38476500, 2024). "The CNS pathological mechanisms may be caused by the elevation of C-C motif chemokine ligand 11 (CCL11) associated with COVID-19, which exhibited similar neuropathology caused by cancer therapy." (PMID 36539855, 2022). "Venn diagram analysis identified a set of common soluble immune mediators with increased levels in all COVID-19 subgroups (from 1.6× up to 8.2×), comprising CCL11, IFN-γ, IL-1Ra, and G-CSF (* below bar charts)." (PMID 40821818, 2025). "The analysis of cord blood samples at Early and Intermediate convalescent COVID-19 showed increased levels of CCL11, CCL3, CCL4, CCL2, IL-1β, IFN-γ, IL1-Ra, G-CSF, and IL-7 and a decrease of IL-10 and IL-2 as compared with HC." (PMID 40821818, 2025). "Conversely, individuals at moderate to severe risk of OSA with concurrent COVID-19 showed reduced levels of serum IL-6, Eotaxin-1/CCL11, and salivary MIP-3α/CCL20 compared to those with mild OSA risk and concurrent COVID-19." (PMID 38476500, 2024). "Over time, the natural course of COVID-19 showed persistently high respiratory interferon concentrations and elevated concentrations of the eosinophil chemokine, CCL-11, despite clinical symptom improvement." (PMID 35397798, 2022). "There was persistent systemic inflammation after 28 days following COVID-19, including elevated concentrations of interleukin (IL)-6, tumour necrosis factor-α, and CCL-11." (PMID 35397798, 2022). "CCL11 (eotaxin-1) which acts through receptor CCR3 was found to be increased in the earlier phase of COVID-19 and its levels remained steady post infection (Khalil, Elemam & Maghazachi, 2021)." (PMID 36353605, 2022). "According to a recent meta-analysis, chemokines (CCL2, CXCL10 and CCL11) were shown to be higher in severe COVID-19 patients than in moderate cases." (PMID 35958594, 2022). "A decreased abundance of a cluster of several leukocyte chemotactic factors (MCP-4, CXCL12, CCL11, CCL19, CCL25, and CCL20) was observed in the COVID-19 cases and associated with a decrease in the cytotoxic T-cell marker CD8A." (PMID 34710339, 2022). "Venn diagram analysis identified a set of common soluble immune mediators with fold change magnitude over 1.5× up to 15.7× in cord blood samples according to mother serum in all COVID-19 subgroups, comprising CCL11, CCL4, IFN-γ, PDFG, and G-CSF (* below bar charts)." (PMID 40821818, 2025). "A dysregulation in cytokine content has been linked to T cell exhaustion in patients who recovered from COVID-19 (n = 39), with higher levels of IL-1β, IL-1RA, IL-7, IL-8, IL-10, IFN-γ, and MIP-1α, and a decrease in IL-9, CCL11, MIP-1β, and RANTES, as compared with healthy controls (n = 43)." (PMID 38549752, 2024).
COVID-19 (continued). "Furthermore, in COVID-19-positive individuals with a moderate to severe OSA risk, lower levels of serum Eotaxin-1/CCL11 (median 1332.5, IQR 1178) were observed in contrast to those with a mild OSA risk (median 1933, IQR 1210, p < 0.05)." (PMID 38476500, 2024). "Interestingly, the profile of this cluster in COVID-19 again shows a mixed Th1/Th2/Th9/Th17 response, together with innate cytokines (IL-1β, IL-6), eosinophil chemokines (CCL11), growth factors, and vasoactive molecules (GM-CSF, HGF, EGF, VEGF)." (PMID 35674675, 2022). "Interestingly, early in COVID-19, there is also a Th2 immune response, mediated mainly by CCL11 and IL-4." (PMID 35397798, 2022). "As a result, early monitoring of CCL2 and CCL11 levels and responding on any elevations could be a potential method for preventing COVID-19 from advancing from mild to severe." (PMID 35958594, 2022). "Interestingly, our gene expression analysis of post-mortem COVID-19 patient lungs revealed that the eosinophil associated genes, CLC, RNASE2 (EDN), and CCL11 were some of the most upregulated genes in COVID-19 lung tissue." (PMID 33777047, 2021). "In addition, CCL11 (eotaxin-1), a major eosinophil chemokine, was significantly increased in COVID-19 lung patient tissue." (PMID 33777047, 2021). "Interestingly, Eotaxin (CCL11), monocyte chemoattractant protein 1 (MCP1), and IL-12p70 were decreased in PC patients compared to both convalescent and healthy controls; some of these chemokines were associated with severe cases of acute COVID-19." (PMID 38326527, 2024). "The unique upregulation of the eosinophil-specific chemoattractant, CCL11, suggests the potential activation of an eosinophil-mediated inflammatory response, which can be one of the mechanisms contributing to myocardial injury and heart failure in COVID-19 patients." (PMID 34262555, 2021). "Data demonstrated that increased levels of CCL11, IFN-γ, IL1-Ra, and G-CSF were observed in cord blood samples from most COVID-19 subgroups, with fold change magnitude from 1.6× to 8.2× as compared with HC." (PMID 40821818, 2025). "In our study, interleukins (IL-1 α, IL-7, IL-17, and IL-18) and chemokines (CCL11 and CXCL1) were found increased in COVID-19-only." (PMID 41516165, 2025). "IFNA1 also presented a robust positive correlation with CCL11, FASLG, and IL23A in severe patients, and their correlation power was gradually enhanced as COVID-19 severity increased." (PMID 36776879, 2023). "An elevated IFNA1 response displayed a strong negative correlation with IL12p40 and CX3CL1, whereas it presented a robust positive correlation with CCL11, FASLG, and IL23A, especially in severe COVID-19 patients." (PMID 36776879, 2023). "In male individuals suffering from COVID-19 it was observed that five inflammatory proteins were significantly higher abundant: OPG, AXIN1, CXCL1, CCL11 and CCL10." (PMID 37832397, 2023). "Data analysis demonstrated an increased order of magnitude (≥3x) for CXCL8, CCL3, IL-6, IFN-γ, G-CSF and decreased order of magnitude (≤0.3x) for CCL11, IL-4, IL-5, IL-10, PDGF and IL-7 in COVID-19 patients throughout the kinetic follow-up." (PMID 36451835, 2022). "In contrast, IL-1β, IL-4, IL-5, IL-12p70, IL-13, IL-17A, CCL11, and VEGF levels predicted severe COVID-19." (PMID 33995342, 2021). "Levels of pro-inflammatory (IFN-γ, IL-1β, IL-6, IL-9, IL-12p70, CCL11) and anti-inflammatory (IL-4, IL-5, IL-10, IL-13) cytokines, as well as VEGF, were higher in severely ill COVID-19 patients as compared to pandemic influenza A(H1N1) subjects." (PMID 33995342, 2021). "Our results showed upregulation of chemotactic factors, including CCL4, CCL8, and CCL11, that all shared CCR5 as their receptor, as a common derangement observed in both diseases; RA and COVID-19." (PMID 32923679, 2020). "Regardless of the COVID-19 stage, cord blood samples from neonates born to mothers with COVID-19 exhibited higher levels of CCL11, IFN-γ, IL-1Ra, and G-CSF as compared with healthy controls." (PMID 40821818, 2025).
COVID-19 (continued). "Increased levels of interleukins (IL-1 α, IL-7, IL-17, and IL-18) and chemokines (CCL11, and CXCL1) were found only in the COVID-19-only, whilst PLWH/COVID-19, had increased levels of four different interleukins (IL-5, IL-6, IL-9, and IL-15) and one chemokine (CXCL10) compared to COVID-19-only." (PMID 41516165, 2025). "Regarding eosinophil chemotaxis, other studies have demonstrated that the migration of eosinophils toward the infected tissue during COVID-19 particularly enhanced numbers of eosinophils in the bronchoalveolar lavage (BAL), likely and partially due to an increase in BAL CCL11 (eotaxin-1)." (PMID 40710346, 2025). "As markers of immune response were elevated in COVID-19-infected mice and exposed patients, we also assessed hippocampal mRNA levels of tumor necrosis factor (TNF)-α, interleukin (IL)-4, interferon (IFN)-γ, and C-C motif chemokine 11 (CCL11 or Eotaxin)." (PMID 39660133, 2024). "The mediators CCL3, CCL4, CCL2, CCL5, IL-12, IL-15, IL-1Ra, and PDGF were higher in healthy volunteers, while the mediators CCL11, CXCL10, IL-1b, IL-6, TNF-a, IFN-g, IL-17, IL-9, IL-10, IL-13, FGF-basic, G-CSF, GM-CSF, IL-7, and IL-2 were increased in COVID-19 positive patients." (PMID 37903875, 2023). "Network analysis of inflammatory mediators in the nasal mucosa and serum showed an anti-inflammatory response (IL-10 upregulation) and T2 inflammatory (CCL11 and CCL24 upregulation) response with co-existent inflammation (upregulation of IL-6 and CXCL8) in early COVID-19." (PMID 35397798, 2022). "However, one meta-analysis found that severe cases of COVID-19 had greater levels of chemokines (CCL2 and CCL11) than moderate ones." (PMID 35958594, 2022). "Meanwhile, COVID-19 displayed an immune profile distinguished by increased Th1 (IL-12, IFN-γ) and Th2 (IL-4, IL-5, IL-10, IL-13) cytokine levels, along with IL-1β, IL-6, CCL11, VEGF, TWEAK, TSLP, MMP-1, and MMP-3." (PMID 33995342, 2021). "Interestingly, as observed in human COVID-19 patients with fatal disease (KO and 1A0) and those with severe disease (6A4) had overall, significantly increased systemic levels of G-CSF, IL-6, IL-10, TNF-α, IL-12 (p40), IL-17A, CCL5, and CCL11 compared to those with moderate disease (6A2 and 1A3)." (PMID 40242753, 2025). "CCL11 has been shown to induce degranulation and EDN release from human eosinophils and contribute to cytolysis of eosinophils in mice which could potentially explain the counterintuitive finding of eosinopenia and elevated secondary granules in COVID-19 patients." (PMID 33777047, 2021). "CCL11, IFN-β, and IFN-γ did not significantly change between day 0 and day 14 and remained elevated after 14 days in patients with COVID-19 in the usual care group compared with healthy volunteers." (PMID 35397798, 2022). "The persistent elevation of mediators such as CCL11, IFN-γ, IL-1Ra, and G-CSF in umbilical cord blood, regardless of the stage of maternal COVID-19, underscores the importance of “in utero priming” and its potential to modulate neonatal immunity in the long term." (PMID 40821818, 2025).
Allergy (40 papers, 2008 to 2025). An allergy is an immune response or reaction to substances that are usually not harmful. "The biological effects of CCL11 are closely associated with its chemotaxis of recruiting eosinophils in inflammatory sites during allergic reactions." (PMID 38906863, 2024). "Another circulating factor that has been heavily studied as an aging marker in relation with neural degeneration is eotaxin-1 (CCL-11), which belongs to a chemokine family and is linked to inflammation and allergic reactions." (PMID 35457154, 2022). "CCL11 is a chemokine originally implicated in the selective recruitment of eosinophils into inflammatory sites during allergic reaction." (PMID 34437596, 2021). "Immunohistochemical assays were carried out in the study group of patients with allergy and gastrointestinal symptoms to reveal positive staining for eotaxin-1 (CCL-11) in 56 (78%) patients, including all patients with eosinophilic esophagitis." (PMID 40284218, 2025). "CCL11 has been shown to promote migration of neutrophils during human allergic reactions and in a murine lung injury model." (PMID 33954115, 2021). "This new knowledge sets the stage for future anti-allergy therapies targeting IKKβ signaling in IECs or oral delivery of anti-CCL11." (PMID 30123215, 2018). "While in the BAL fluid, as expected, elevated levels of CCL11 were only found in the allergy group, in serum both, control mice as well as allergic mice, displayed high levels of CCL11." (PMID 27445696, 2016). "The chemokine CCL2, which is an effective attractant for monocytes, was significantly increased in the allergy model, whereas surprisingly CCL11, a signaling molecule attracting eosinophils was significantly decreased in the serum of allergic mice." (PMID 27445696, 2016). "Tim Williams tells the exciting story about the discovery of eotaxin (CCL11) and its involvement in eosinophil recruitment during allergic diseases." (PMID 26579123, 2015). "These patients showed high systemic levels of the CCL11, a cytokine involved in the pathogenesis of allergy." (PMID 23049769, 2012). "In addition, we observed evidence of intercellular communication via genes implicated in type 2 immunity (CCL11, CCL13, CD5L, IL4, IL5, IL13, IL24) and allergy-linked inflammation (CCL19)." (PMID 35483355, 2022). "CCL11 is a strong eosinophil chemoattractant that mediates allergic diseases." (PMID 27149601, 2016). "Moreover, CCL11, which has been associated to TH2-responses in allergic reactions and is able to recruit TH2 lymphocytes, showed a negative association with Pv infection, supporting the hypothesis that Pv malaria in pregnancy triggers a TH1 response." (PMID 32365058, 2020). "Eosinophils expressing the chemokine receptor CCR3 are attracted by the activation of the chemokine eotaxin family, which consists of eotaxin-1 (CCL11), eotaxin-2 (CCL24), and eotaxin-3 (CCL26), in allergic diseases." (PMID 39962262, 2025). "Eotaxin-1/CCL11 is a chemokine primarily responsible for recruiting eosinophils to inflammation sites, especially in the context of allergic reactions." (PMID 38476500, 2024). "Eosinophil attractants, CCL11 and CCL13 chemokines, are involved in allergy responses." (PMID 37598287, 2023). "Oral administration of CCL11 to IKKβΔIEC mice during oral allergen challenge enhanced allergic responses to levels in wild-type mice, confirming the role of IEC-derived eotaxin as regulator of the effector phase of allergy following allergen challenge." (PMID 30123215, 2018). "Eotaxins (ccl11 and ccl24) and regulated on activation normal T cell expressed and secreted (RANTES or ccl5) are potent chemoattractants that mediate eosinophil chemotaxis and allergy signaling." (PMID 30252910, 2018). "Indeed, during allergy and anti-helminth immunity, epithelial cells of damaged barriers release alarmins including IL-25, IL-33, and thymic stromal lymphopoietin (TSLP), but also chemokines such as CXCL1 and CCL11, to promote cell recruitment and inflammation." (PMID 40943268, 2025).
Cognitive impairment (27 papers, 2015 to 2025). Abnormal cognition is characterized by deficits in thinking, reasoning, or remembering. "CCL11 can cause cognitive impairment by inhibiting neurogenesis, reducing synaptic density, and inducing neuronal cytotoxicity leading to neuronal damage and death." (PMID 39011039, 2024). "Eotaxin/CCL11 is of particular interest as it is a chemokine sufficient to cause cognitive impairment, microglial reactivity in the hippocampus and reduced hippocampal neurogenesis." (PMID 38798554, 2024). "Of note, CCL11, a cytokine associated with cognitive impairment remained persistently elevated in both SARS-COV-2 and H1N1 models." (PMID 37693763, 2023). "A study from France explored the association between cognitive impairment and the plasma chemokine C-C motif ligand 11 (CCL11), a potential negative regulator of neurogenesis." (PMID 35885866, 2022). "Evidence points to a strong association between high concentrations in blood CCL11 and the decline in neurogenesis and cognitive impairments, and this fact is observed in aged subjects." (PMID 28149283, 2016). "Elevated levels of CCL11, a chemokine known to inhibit neurogenesis, and associations with cognitive impairment and reduced hippocampal volumes further support this hypothesis." (PMID 40589858, 2025). "CCL11 levels may be associated with greater anxiety, depression, and cognitive deficits among individuals who use MA." (PMID 37996407, 2023). "Age-related increases in CCL-11 are associated with cognitive impairments in executive functions and episodic and semantic memory, and therefore, this chemokine has been described as an “Endogenous Cognition Deteriorating Chemokine” (ECDC) or “Accelerated Brain-Aging Chemokine” (ABAC)." (PMID 32887304, 2020). "Notably, CCL11, a cytokine associated with cognitive impairment, remained persistently elevated in the CSF over time, suggesting that isolated respiratory infection with SARS-CoV-2 can result in prolonged changes in CSF cytokine profiles, leading to persistent neuroinflammation." (PMID 37693763, 2023). "Recently, white-matter-selective microglial reactivity and increased levels of the proinflammatory chemokine CCL11 leading to impaired hippocampal neurogenesis was suggested as pathophysiological mechanisms behind cognitive impairment." (PMID 36817925, 2023). "A study shows that with the increase of age, the levels of CCL11 in plasma and cerebrospinal fluid of humans and mice increase, which will reduce synaptic plasticity, inhibit nerve regeneration, and lead to cognitive impairment." (PMID 37441611, 2023). "Several studies have suggested CCL11 ultimately plays a role in cognitive impairment and therefore, either directly or indirectly, affect neurons." (PMID 28950005, 2017). "These suggest a role for CCL11 in the pathological mechanism of cognitive impairment." (PMID 39011039, 2024). "Notably, it was found that CCL11 and its receptor were involved in cognitive impairment in AD patients and AD model animals." (PMID 37441611, 2023). "Thus, blood-borne CCL11 may be involved in the process of AD in aging, and peripheral CCL11 concentrations might be able to predict cognitive impairment." (PMID 34044860, 2021). "Importantly, CCL11 has been shown to directly regulate neurogenesis, such that increased circulating eotaxin was associated with reduced neurogenesis in aged mice and infusion of CCL11 into young mice resulted in decreased neurogenesis and cognitive impairment." (PMID 31434191, 2019). "In this paper, we review the roles and regulatory mechanisms of pro-inflammatory chemokines (CCL2, CCL3, CCL4, CCL5, CCL11, CCL20, and CXCL8) in cognitive impairment." (PMID 39011039, 2024). "CCL11 was shown to pass the BBB and was identified as a crucial mediator of decreased neurogenesis and increased cognitive impairment in mice." (PMID 30413208, 2018).
Cognitive impairment (continued). "Recent research has shown that young blood can reverse cognitive impairments and improve cognitive function by regulating related cytokines, such as Growth Differentiation Factor 11 (GDF11) and C-C motif Chemokine 11 (CCL11)." (PMID 26317549, 2015). "Of interest, human patients with long-COVID and associated cognitive impairment (i.e., “brain fog”) following a mild respiratory SARS-CoV-2 infection had similar elevated CCL11 plasma levels compared to patients without cognitive impairment." (PMID 36034552, 2022). "Patients with cognitive impairment in PCS showed higher CCL11/eotaxin-1 plasma values than patients with non-cognitive PCS symptoms, a cytokine that leads to specific reactivity of hippocampal microglia and impaired hippocampal neurogenesis in mice after systemic application." (PMID 38438479, 2024).